TIMP1 (TIMP metallopeptidase inhibitor 1)
Diseases named in the same sentence as TIMP1 in open-access papers (continued):
Sharing a sentence is not in itself a finding about the gene and the disease.
multiple sclerosis (9 papers, 2011 to 2022). A progressive autoimmune disorder affecting the central nervous system resulting in demyelination. "TIMP-1 also plays an important MMP-dependent role in demyelinating disease, as illustrated by increased levels of demyelination and myelin pathology in TIMP-1 deficient mice in the mouse model of multiple sclerosis, experimental autoimmune encephalomyelitis (EAE)." (PMID 21631912, 2011). "For example, release of astrocyte-derived TIMP-1 in an experimental autoimmune encephalomyelitis (EAE) model of multiple sclerosis has a protective effect and results in myelin sparing and attenuates the effect of IL-1β on the wound healing responses in vitro." (PMID 31616247, 2019). "Likewise, our findings that post-MI patients exhibited increased TIMP-1 and -2 mRNA levels in PBMCs are in line with previous studies of patients with multiple sclerosis." (PMID 25153995, 2014).
myeloma (9 papers, 2014 to 2024). "In the current study, we demonstrated that the TIMP1 protein levels in BM plasma (BM microenvironment) and the TIMP1 mRNA expression in malignant plasma cells from patients with MM (myeloma cells) were higher than those in patients with MGUS." (PMID 36768545, 2023). "Recombinant TIMP1 promoted, whereas neutralised anti-TIMP1 antibodies inhibited fibroblast invasion, supporting the invasion of myeloma cells." (PMID 36768545, 2023). "Our comparison between TIMP1 levels at diagnosis and at CR, positive correlation between TIMP1 and MM tumour burden, implied that myeloma cells themselves produced TIMP1." (PMID 36768545, 2023). "TIMP1 mRNA and protein levels were elevated when patients progressed from monoclonal gammopathy of undetermined significance or smouldering myeloma to MM." (PMID 36768545, 2023). "Since the flow cytometric analysis at CR exhibited no abnormal clonal plasma cells in the BM, this result supports the idea that myeloma cells produce higher amounts of TIMP1." (PMID 36768545, 2023). "Next, to determine the cytokine-like functions of TIMP1, human recombinant TIMP1 purified from a mouse myeloma cell line was used to stimulate pFs in increasing concentrations at different time points." (PMID 35140332, 2022). "RT-PCR analysis revealed that 5TGM1 cells and osteoblasts express TIMP-1 and we observed significantly higher levels of TIMP-1 in serum derived from multiple myeloma bearing animals compared to control." (PMID 28241871, 2017). "In keeping with this observation, we also found that serum from human multiple myeloma patients contained significantly higher levels of TIMP-1 compared to healthy controls." (PMID 28241871, 2017). "Furthermore, GSEA also demonstrated enrichment of migration- and chemokine-related gene expression, implying that TIMP1 conferred the ability to attract myeloma cells to fibroblasts." (PMID 36768545, 2023). "An increase in the endogenous MMP inhibitor TIMP-1 was detected in patients with multiple myeloma, which may account for the reduction in MMP-7 activity, although it is likely that other mechanisms also contribute." (PMID 28241871, 2017). "A statistically significant reduction in TIMP1 expression was observed, accompanied by an increase in CD82B and CRISP3 expression, in the myeloma (MM) group with a favorable prognosis compared to the MM group with an unfavorable prognosis (p < 0.05)." (PMID 39769169, 2024). "We observed that systemic MMP-7 activity was reduced in tumor-bearing mice and, in patients with multiple myeloma this reduced activity was concomitant with increased levels of the endogenous MMP inhibitor, tissue inhibitor of metalloproteinases-1 (TIMP-1)." (PMID 28241871, 2017). "We found a significant effect of TIMP1 on fibroblast invasion in the ECM; we speculated that the fibroblast could support myeloma cell invasion and expansion into ECM." (PMID 36768545, 2023).
oral cancer (9 papers, 2014 to 2023). "MMPs such as MMP-9 or their inhibitors like TIMP-1 are associated with oral cancer metastasis and invasion." (PMID 31772143, 2019). "Our findings confirm that the HAS2-mediated MMP1 and TIMP1 changes are most likely responsible for the mechanisms underlying CAF-mediated promotion of the migration, invasion and EMT of oral cancer cells." (PMID 27884164, 2016). "Furthermore, in a study on the progress and invasion of oral cancer, the author also used a co-IP experiment to prove the interaction between TIMP1 and MMP9." (PMID 36800936, 2023). "In summary, the data presented here demonstrate that HAS2, which is expressed by CAFs, may facilitate the migration, invasion and EMT of oral cancer cells by disturbing the balance between MMP1 and TIMP1." (PMID 27884164, 2016). "Thus, miR-196 appear to fine-tune the invasion mechanism in oral cancer by inhibiting NME4, leading to the activation of p-JNK and MMP1/9 and suppression of TIMP1." (PMID 25233933, 2014).
pulmonary hypertension (9 papers, 2013 to 2024). Increased pressure within the pulmonary circulation due to lung or heart disorder. "These contradictory results regarding the TIMP1 under hypoxia and monocrotaline pulmonary hypertension model in rats indicated that the beneficial effect of artificially increasing TIMP1 depended on the primary injury involved and its balance with MMPs." (PMID 38830933, 2024). "In the present study, we used transcriptome sequencing to verify the increase in ECM deposition and the decrease in the expression of the hub gene TIMP1 in mice with hypoxia-induced pulmonary hypertension (HPH)." (PMID 38830933, 2024). "Crocin, a natural MMP inhibitor, was found to reduce inflammation, decrease MMPs levels, increase Timp1 expression levels, and attenuate hypoxia-induced pulmonary hypertension in mice." (PMID 38830933, 2024). "The role of TIMP-1 in development of pulmonary hypertension and vascular remodeling is controversial." (PMID 30453980, 2018). "In addition, overexpressing adenovirus TIMP1 in MCT-induced pulmonary hypertension in rats reduced pulmonary vascular remodeling, suggesting that balancing MMPs/TIMP1 can reverse the disease." (PMID 38830933, 2024). "Taken together, our results suggest that the MMPs/TIMP1 imbalance in hypoxic pulmonary hypertension may also play an important role in pulmonary hypertension development." (PMID 38830933, 2024). "However, another study by the same group in hypoxia-induced pulmonary hypertension in rats found that overexpressing adenovirus TIMP1 aggravated pulmonary hypertension." (PMID 38830933, 2024). "Previous work suggests that an imbalance of TIMP-1 and matrix metalloproteinases may play a role in severe pulmonary vascular remodeling in pulmonary hypertension." (PMID 24278261, 2013).
renal carcinoma (9 papers, 2010 to 2025). A carcinoma arising from the epithelium of the renal parenchyma or the renal pelvis. "Furthermore, we investigated the functional roles of TIMP1 and the underlying biological signal pathway in renal cancer cells." (PMID 35281807, 2022). "For example, TIMP1+ myCAFs in renal carcinoma exhibit lactylation-dependent pro-angiogenic signatures." (PMID 40565047, 2025). "To confirm these results, we compared the mRNA expression of TIMP1 in Oncomine datasets (Beroukhim, Jones, and Yusenko) and it was shown that TIMP1 was highly expressed in renal cancer samples." (PMID 35281807, 2022). "It has been shown that overexpression of TIMP-1 has a radiosensitizing effect in a renal carcinoma cell line." (PMID 31726667, 2019). "TIMP-1 over-expression radio-sensitizes the renal cancer cells to gamma radiation and also shows elevation of TIMP-2 protein level as well as decrease of MMP-2 activity." (PMID 27659937, 2016). "TIMP-1 immunohistochemical studies have shown increased TIMP-1 immunoreactivity in gastric, breast and renal carcinomas." (PMID 20459644, 2010). "Hence, we aimed to explore the relationship between the expression of TIMP1 and clinicopathological factors in renal cancer." (PMID 35281807, 2022). "T1Pr αMT1, the GPI-anchored designer TIMP-1 created in this study, is a potent MT1-MMP inhibitor with the potential of being further developed into an experimental therapeutic for renal carcinoma treatment." (PMID 30641935, 2019).
gingivitis (8 papers, 2012 to 2026). A disorder involving inflammation of the gums; may affect surrounding and supporting structures of the teeth. "The aim of the present study was to evaluate the effect of adjunctive chlorhexidine (CHX) mouthrinse on gingival crevicular fluid (GCF) MMP-8 and TIMP-1 levels in plaque-associated gingivitis." (PMID 24886536, 2014). "The TIMP-1 levels were significantly higher in the gingivitis and stage I group than in the stage II and III group." (PMID 33916950, 2021). "In this short term, randomized, placebo controlled clinical study, which is a continuation of previously published studies, the effectiveness of CHX as an adjunct to daily plaque control on both clinical and GCF MMP-8 and TIMP-1 levels were evaluated in gingivitis patients." (PMID 24886536, 2014). "For discriminating health vs gingivitis groups, the predictor variables resulting from the CART analysis included MMP-9, TIMP-1." (PMID 33742017, 2021).
keratoconus (8 papers, 2016 to 2025). A degenerative, structural disorder of the eye, characterized by a cone-shaped protrusion of the cornea. "The analysis of individual TIMPs in terms of their usefulness as potential predictors of keratoconus showed high results of diagnostic sensitivity and specificity for all TIMPs, in particular for TIMP-1 and TIMP-2." (PMID 38398480, 2024). "Significant associations between the severity of keratoconus and pairs of t-PA/TIMP-1 and t-PA/PAI were detected in our study." (PMID 26881061, 2016). "Genotype and allelic frequencies of COL4A4 rs2228557 and TIMP-1 rs4898 polymorphisms between keratoconus (KC) patients and healthy controls." (PMID 32864060, 2020). "Statistical univariate analysis of TIMP-1 for usefulness as a potential predictor of keratoconus showed its sensitivity of 94% and specificity of 90% which demonstrates the strong involvement of TIMP-1 in the development of keratoconus." (PMID 38398480, 2024). "The presented study shows that the median TIMP-1 concentration in blood serum in patients with keratoconus was more than 2.5 times reduced compared to the control group." (PMID 38398480, 2024). "Genetic studies on TIMP-1 expression have shown reduced expression in the corneal tissue of patients with keratoconus." (PMID 38398480, 2024). "TIMP1 expression has also been reported in several corneal disease conditions, including BK and keratoconus." (PMID 37895034, 2023). "Correlation of clinical and keratometric parameters with COL4A4 (rs2228557) and TIMP-1(rs4898) in keratoconus patients." (PMID 32864060, 2020). "High diagnostic sensitivity and specificity values of TIMP-1 and TIMP-2 and high diagnostic specificity values of TIMP-3 and TIMP-4 in relation to keratoconus were demonstrated, which confirms their strong role in the etiopathogenesis of this disease, especially when they all interact together." (PMID 38398480, 2024). "In histological examinations of normal corneas, TIMP-1 expression was detected in epithelial and endothelial cells, as well as in smaller amounts in stromal keratocytes, while increased TIMP-1 expression of stromal keratocytes was found in scarred keratoconus corneas." (PMID 38398480, 2024). "Statistical univariate analysis of TIMP-3 for its usefulness as a potential predictor of keratoconus showed itssensitivity of 54% and specificity of almost 90% which probably indicates its smaller importance in the etiopathogenesis of keratoconus compared to TIMP-1 and TIMP-2." (PMID 38398480, 2024). "The aim of the study was to determine the concentration of the TIMPs TIMP-1, TIMP-2, TIMP-3, and TIMP-4 in the blood serum samples of patients with keratoconus compared to the control group." (PMID 38398480, 2024). "TIMP-1, TIMP-2, TIMP-3, and TIMP-4 values were analyzed for their usefulness as potential predictors of keratoconus." (PMID 38398480, 2024). "In addition, TIMP1-EGFR, which was functioned as a metalloproteinase blocker in healthy corneas, were disappeared in keratoconus, indicating that its deficiency might be one of the underlying causes of keratoconus." (PMID 35821117, 2022). "In the current study, we have determined the associations between nine mediators (IL-6, IL-10, CXCL8/IL-8, CCL5/RANTES, MMP-9, MMP-13, TIMP-1, t-PA, and PAI-1) in the tear fluid of keratoconic patients covering the whole spectrum of the disease (from subclinical to manifest keratoconus)." (PMID 26881061, 2016).
kidney damage (8 papers, 2016 to 2024). "It has been reported that plasma levels of TIMP1 are associated with early diabetic neuropathy and nephropathy in patients with type 1 diabetes." (PMID 36960398, 2023). "Rather, OPN/TIMP-1 remain high—as does TEC shedding—as kidney damage continues, leading to persistent kidney failure." (PMID 39440014, 2024). "Several other biomarkers were proposed for detecting kidney damage caused by OTA, such as lipocalin-2, tissue inhibitor of metalloproteinases-1 (Timp-1), clusterin, osteopontin, and vimentin, although KIM-1 was the most promising one." (PMID 37125184, 2023). "Although there is a controversy about the MMP-9 and Timp-1 relationship with kidney damage and CKD, some studies showed a contribution to fibrosis by the higher expression of MMP-9 and lower expression of Timp-1, and others revealed contrary observations." (PMID 35628203, 2022). "However, the observed interaction between TIMP-1 and nephropathy-status should be interpreted with caution as we cannot exclude the play of chance." (PMID 28446168, 2017). "In contrast, plasma TIMP-1 was positively associated with all-cause mortality in patients without nephropathy at baseline." (PMID 28446168, 2017).
liver cancer (8 papers, 2014 to 2025). An epithelial or non-epithelial malignant neoplasm that arises from the liver. "In liver cancer, TIMP1 paradoxically enhances metastatic niche formation by recruiting neutrophils, despite its canonical role as a metalloproteinase inhibitor." (PMID 40687427, 2025). "Previous studies have demonstrated that liver cancer patients with lower serum TIMP-1 concentrations have significantly better overall survival than those with higher serum TIMP-1 concentrations." (PMID 35935258, 2022). "The overexpression of TIMP-1 has been confirmed to increase the migration of liver cancer cells, and inhibit apoptosis in tumor cells (Li, Fridman & Kim, 1999)." (PMID 35935258, 2022). "Similarly, in liver cancer, TIMP1 paradoxically facilitates metastasis by modulating the hepatic microenvironment, underscoring context-dependent effects." (PMID 40687427, 2025).
malaria (8 papers, 2011 to 2025). Malaria is a serious and sometimes fatal disease caused by a parasite that commonly infects a certain type of mosquito which feeds on humans. "On the contrary, TIMP-1 is associated with signs and symptoms of severe malaria, and MMP-8 levels are elevated in patients with severe or uncomplicated P. falciparum malaria." (PMID 25436884, 2013). "There also a range of other mediators, such as IL-17, IL-4, nitric oxide, C-C chemokine RANTES, matrix metalloproteinases 8 (MMP8s) and tissue inhibitor of metalloproteinases 1 (TIMP1) that have been linked to disease severity in malaria-infected individuals." (PMID 23294670, 2013). "In the light of these results, it may be argued that TIMP-1 and MMP-8 may predict the severity of malaria." (PMID 25436884, 2013).
osteoporosis (8 papers, 2012 to 2025). A condition of reduced bone mass, with decreased cortical thickness and a decrease in the number and size of the trabeculae of cancellous bone (but normal chemical composition), resulting in increased fracture incidence. "TIMP1 has been implicated in the development of osteoporosis by regulating the apoptosis of osteoblasts." (PMID 33733597, 2021). "The enzyme analysis results of all these studies revealed that MMP2, MMP9, TIMP1, and TIMP2 were low and cathepsin K was high in MPS III patients, and that the patients had low bone density and increased osteoporosis risk." (PMID 40104299, 2025). "The therapeutic effect of TIMP1 inhibition on osteoporosis was evaluated in a type 2 diabetic mouse model." (PMID 39578773, 2024). "In this study, we also measured the expression of miR‐138 and TIMP1 in bone tissue samples collected from osteoporosis patients." (PMID 33733597, 2021). "In summary, TIMP1 exerts a critical effect on osteoblast apoptosis and the development of osteoporosis." (PMID 33733597, 2021). "Suppression of TIMP1 expression alleviated the progression of osteoporosis in type 2 diabetic mice." (PMID 39578773, 2024). "Therefore, it can be concluded that oestrogen deficiency could induce the apoptosis of osteoblasts and lead to osteoporosis in post‐menopausal females via modulation of the HOTAIR/miR‐138/TIMP1 signalling axis." (PMID 33733597, 2021). "Therefore, although this study suggested a novel role of TIMP1 in the acceleration of osteoblast apoptosis, it remains unclear whether ER stress and miR‐138 are significantly involved in osteoporosis." (PMID 33733597, 2021). "In COPD patients with osteoporosis, circulating MMP-9 levels were increased, whereas TIMP-1 and -2 were not different and associated with bone loss (reduced bone mass and osteoporosis)." (PMID 36991363, 2023). "In a further study, Zhang PF found that serum MMP-9/TIMP-1 ratios in COPD patients with osteoporosis were significantly higher (high MMP-9, low TIMP-1) than in patients with normal bone mineral density (BMD) and that these ratios were negatively correlated with BMD." (PMID 36991363, 2023). "Finally, a higher expression level of TIMP1 protein also increased the viability and reduced the apoptosis of osteoblasts, confirming the role of HOTAIR in the pathogenesis of osteoporosis among post‐menopausal females." (PMID 33733597, 2021). "Although measurements of circulating MMP-9 and TIMP-1 allowed us to detect effects of exercise, as of today, they have no real role in the diagnosis of osteoporosis and/or follow-up of osteoporotic patient's response to treatment." (PMID 32071923, 2020).